ALK (ALK receptor tyrosine kinase)
Diseases named in the same sentence as ALK in open-access papers (continued):
Sharing a sentence is not in itself a finding about the gene and the disease.
CNS tumors (13 papers, 2017 to 2025). "From a subset of 2453 neoantigens identified in the solid and CNS tumor sub-cohort, we commonly predicted four neoepitopes from eight cell line models, of which two neoepitopes are associated with recurrent mutations H3-3A K27M and ALK F1174L." (PMID 41312385, 2025). "The ALK gene can be rearranged, amplified or mutated in pediatric CNS tumors." (PMID 39409964, 2024). "The expression of wt-ALK in a large number of CNS tumors was expected, as it is known that ALK is expressed in brain tissues." (PMID 39594806, 2024). "This compound can be given with food and penetrates the human brain, and thus presents itself as an option for the treatment of CNS tumors with ALK alterations such as EPN and MB." (PMID 36839989, 2023). "The current case reiterates the activity of ALK inhibitors within the CNS and suggests that radiotherapy may potentiate the permeability of ALK inhibitors in CNS tumors addicted to ALK signalling." (PMID 28409069, 2017). "In tumors with priority level 1 targets, several known actionable targets such as ALK, BRAF and NTRK were detected in extracranial solid and CNS tumors." (PMID 38357207, 2024). "Moreover, Entrectinib, a potent CNS-penetrant inhibitor of TRKA/B/C, ROS1 and ALK, was also evaluated to treat children and young adults with solid or primary CNS tumors harboring NTRK, ROS1 or ALK aberrations." (PMID 36839989, 2023).
lung (12 papers, 2017 to 2025). "In this study, NGS analysis was performed using a biopsy specimen of liver metastasis after resistance to lorlatinib treatment, and ALK I1171S and G1269A compound mutation was found." (PMID 31943796, 2020). "The study cohort comprised 31 ALK-positive, 40 EGFR-positive and 43 ALK/EGFR-negative lung ADC patients." (PMID 34125345, 2022). "Thus, in cases where metastatic samples from brain are tested as the initial screen for ALK fusions and found to be RT-PCR-positive, it may be useful to also test a sample from the lung primary tumor or to reflex the metastatic sample to NGS." (PMID 28763012, 2017). "We performed comparative mRNA expression profiling of 31 ALK-positive, 40 EGFR-positive and 43 ALK/EGFR-negative lung ADC focused on immune gene expression." (PMID 34125345, 2022). "Although concurrent EGFR-mutation and ALK-rearrangement in lung ADC is more frequent than initially anticipated, we detected no ALK fusion-protein expression, i.e. no sign of ALK-rearrangement, in any of the 23 EGFR-mutated patients." (PMID 29899852, 2018). "Overall survival (OS) for Stage IV lung ADC at initial diagnosis were analyzed in patients with BRAF V600E or with undetected mutation (no driver mutation/fusion detected in BRAF, EGFR, KRAS, ALK, ROS1, RET, HER2, or MET genes)." (PMID 31234388, 2019).
hematologic malignancies (10 papers, 2012 to 2024). "Anaplastic lymphoma kinase (ALK) is a receptor tyrosine kinase that is frequently involved in gene fusions in hematological disorders." (PMID 22928112, 2012). "Interestingly, there are ongoing clinical trials evaluating the use of ALK inhibitors in various solid tumors and hematological malignancies (NCT05384626, NCT04925609)." (PMID 38339401, 2024). "Immunohistochemical (IHC) stain for detection of ALK over-expression has been a well-established method for detection of ALK rearrangements, such as NPM-ALK, in hematological malignancies for years." (PMID 23951022, 2013). "Genomic characterization of pediatric hematologic malignancies in our cohort identified potential therapeutic targets in nearly 40% of patients (7/18, 38.9%), including the consideration of inhibitors targeting MEK (n=3), receptor tyrosine kinases (ALK n=2, PDGFRB n=1), FLT3 (n=1), and PD-L1 (n=1)." (PMID 39687881, 2024).
gastrointestinal tumors (9 papers, 2015 to 2025). "Given the limited data on the efficacy of ALK inhibitors in pretreated patients with ALK fusion-positive gastrointestinal (GI) cancers, an international data set and molecular case series of GI tumors were analyzed." (PMID 41374970, 2025). "IMTs are the much more common types of ALK-positive gastrointestinal neoplasm, far outnumbering metastatic NSCLCs." (PMID 40224190, 2025). "While the clinical characteristics of ALK-fusion gastrointestinal tumors have been previously documented, there is a dearth of data regarding the efficacy of ALKi in patients with ALK-positive CRC due to its rarity in colorectal malignancies." (PMID 38740834, 2024). "Likewise, other rare ALK-altered digestive system neoplasms confront therapeutic decision challenges." (PMID 41246301, 2025).
hematologic cancers (8 papers, 2011 to 2025). "Earlier studies have demonstrated crizotinib’s potential in treating hematological cancers with ALK rearrangements." (PMID 41357210, 2025). "Oncogenic receptor tyrosine kinases including anaplastic lymphoma kinase (ALK) are implicated in numerous solid and hematologic cancers." (PMID 31334113, 2019). "In this study, we asked if the H2O2-induced RU/RR conversion also exists in hematopoietic cancers such as ALK+ALCL." (PMID 29609590, 2018). "Anaplastic lymphoma kinase (ALK) is a tyrosine kinase receptor which has been implicated in numerous solid and hematologic cancers." (PMID 27049722, 2016). "However, ALK is also altered in a wide array of other solid tumors, as well as in hematologic cancers, with important clinical implications." (PMID 37773318, 2023).
blood tumors (4 papers, 2012 to 2024). "In ALK-positive solid and hematological tumors, activating mutations in the tyrosine kinase domain of the ALK oncogene are considered driver mutations." (PMID 35207754, 2022). "This hematologic neoplasm shows a characteristic ALK positivity in immunohistochemical examination and correspondingly, ALK fusion genes in the molecular analysis." (PMID 38602523, 2024). "Thus, ALK has been considered as an important therapeutic target for the treatment of NSCLC and various blood tumors harboring an ALK fusion." (PMID 35004700, 2021).
psychiatric disorder (3 papers, 2011 to 2024). A disorder characterized by behavioral and/or psychological abnormalities, often accompanied by physical symptoms. "The mechanism underlying psychiatric adverse events (AEs) caused by ALK inhibitors remains unclear, despite ALK’s involvement in regulating the dopamine D2 receptor (D2R), which is implicated in psychiatric disorders." (PMID 39001519, 2024). "Psychiatric disorders leading to treatment discontinuation concerned hallucinations and persecution mania (grade NR) in two ALK-positive patients with BM and LMC." (PMID 33613692, 2021). "It is noteworthy, that two of five patients with AE-related treatment cessation were discontinued due to psychiatric disorders, effects that have not been reported for other ALK or ROS1-TKIs." (PMID 33613692, 2021).
brain disease (2 papers, 2018 to 2022). "An unanswered clinical question is whether withhold brain radiation in patients receiving second and third generation ALK inhibitors, since these agents penetrate the blood-brain barrier better than crizotinib and offer a significant control of brain disease." (PMID 30052658, 2018).
neurological disease (2 papers, 2014 to 2023). "Overall, our data shed light on the activity-dependent and crucial role of Alk in the control of essential physiological functions in mice, in agreement with the extremely severe neurological disorders observed in patients carrying the most aggressive ALK germline mutations." (PMID 24811761, 2014). "In particular, we sought to determine whether these mice reproduce the severe neurological disorders observed in patients with de novo heterozygous germline activating ALK mutations." (PMID 24811761, 2014). "In the present paper, we sought to determine whether KI AlkF1178L mice phenocopy the severe neurological disorders observed in patients with de novo germline activating ALK mutations." (PMID 24811761, 2014).
central nervous system disease (1 paper, 2016). "Additionally, ALK-positive NSCLC patients with emergent central nervous system disease were more likely to benefit from treatment." (PMID 27835601, 2016).
epithelial neoplasm (1 paper, 2023). A benign or malignant neoplasm that arises from and is composed of epithelial cells. "TFG is a well-known fusion partner in a variety of mesenchymal and epithelial neoplasms of different organs, mostly fused to other receptor tyrosine kinases such as ALK, ROS1, and NTRK." (PMID 36690805, 2023).
heart disease (1 paper, 2022). "If the patient had risk factors such as older age and heart disease before therapy, it should be noted that ALK-TKIs may lead to HF in clinical practice." (PMID 35370632, 2022).
infectious disease (1 paper, 2017). A disorder directly resulting from the presence and activity of a microbial, viral, or parasitic agent in humans. "The data demonstrate a strong positive association among the frequencies of positive memory B-cells for TIM-3), and infectious disease agents (biofilm, influenza B) as well as tumor-associated antigen (ALK)." (PMID 28723950, 2017).
neoplastic disorders (1 paper, 2025). "Crizotinib is an ALK (anaplastic lymphoma kinase) mutation-targeting agent employed in the management of ALK-positive non-small cell pulmonary carcinoma (NSCLC) and various other neoplastic disorders." (PMID 40299448, 2025).
retinopathy (1 paper, 2020). "The therapeuticpotential of ALK-001 was demonstrated in a murine model ofABCA4-associated retinopathy, by showing a reduced A2Edimer formation and lipofuscin accumulation compared to age-matchedwild-type mice." (PMID 32278709, 2020). "A phase 1 study, in which ALK-001 was administered to 40healthy adult volunteers, has been completed (NCT02230228), after which the phase II study, where 50ABCA4-associated retinopathy cases were administeredwith either ALK-001 or placebo at a daily basis, was initiated." (PMID 32278709, 2020).
ALK also shares sentences with these, for which no sentence is quoted: acute lymphoblastic leukemia (11 papers); large cell carcinoma (11); hypertriglyceridemia (10); alveolar rhabdomyosarcoma (8); renal medullary carcinoma (7); bladder cancer (6); pancreatic ductal adenocarcinoma (6); Renal neoplasm (6); dermatofibrosarcoma protuberans (5); head and neck cancer (5); hepatosplenic T-cell lymphoma (5); peripheral neuropathy (5); Sézary syndrome (5); collecting duct carcinoma (4); head and neck squamous cell carcinoma (4); Langerhans cell histiocytosis (4); pediatric tumors (4); small lymphocytic lymphoma (4); solitary fibrous tumor (4); T-lymphoblastic lymphoma (4); tuberculosis (4); acute leukemia (3); anaplastic carcinoma (3); bronchioloalveolar carcinoma (3); dyslipidemia (3); endometrial stromal sarcoma (3); follicular carcinoma (3); follicular lymphoma (3); ganglioneuroblastoma (3); kidney cancer (3).
A further 254 diseases each share a sentence with ALK in 3 papers or fewer.